KCNQ1OT1 (KCNQ1 opposite strand/antisense transcript 1)
Diseases named in the same sentence as KCNQ1OT1 in open-access papers (continued):
Sharing a sentence is not in itself a finding about the gene and the disease.
rectal cancer (5 papers, 2020 to 2025). A primary or metastatic malignant neoplasm that affects the rectum. "For example, lncRNA KCNQ1OT1 was proposed as a diagnostic and prognostic factor in colon adenocarcinoma and rectal cancer, which played a role in enhancing drug resistance in tumor cells." (PMID 38796816, 2024). "Based on network modeling, lncRNA KCNQ1OT1 (AUC>0.85) and SNHG1 (AUC>0.94) were unveiled as common diagnostic biomarkers for the initiation and metastasis of colon and rectal cancers." (PMID 33194594, 2020). "In particular, KCNQ1OT1 and SNHG1 function in colon and rectal cancers via different ceRNA mechanisms." (PMID 33194594, 2020). "Especially, the KCNQ1OT1 and SNHG1 were unveiled as common lncRNA biomarkers with critical roles in the initiation and metastasis of colon and rectal cancers via distinct ceRNA mechanisms." (PMID 33194594, 2020). "LncRNA KCNQ1OT1 and SNHG1 may contribute to the progression of colon and rectal cancers through distinct mechanisms." (PMID 33194594, 2020). "Based on our computational model, KCNQ1OT1 and SNHG1 possessing hub nodes properties in all of the four context-specific ceRNA networks, were identified as shared lncRNA biomarkers in colon and rectal cancer, revealing their critical role in colorectal carcinogenesis." (PMID 33194594, 2020). "As an interesting result, we found that KCNQ1OT1 and SNHG1 could regulate the initiation and metastasis of colon and rectal cancers through distinct ceRNA regulatory axes, which have not been reported in previous studies." (PMID 33194594, 2020).
acute kidney injury (4 papers, 2021 to 2023). Sudden and sustained deterioration of the kidney function characterized by decreased glomerular filtration rate, increased serum creatinine or oliguria. "In the acute kidney injury mouse model, KCNQ1OT1 was highly expressed, and knockdown of the KCNQ1OT1 promoted cell proliferation and prevented apoptosis and inflammation." (PMID 37189386, 2023). "In addition, knockdown of KCNQ1OT1 would reduce the activation of NLRP3 inflammasome in acute kidney injury." (PMID 36278219, 2022).
acute respiratory distress syndrome (4 papers, 2021 to 2022). Progressive and life-threatening pulmonary distress in the absence of an underlying pulmonary condition, usually following major trauma or surgery. "For instance, in terms of LPS-triggered inflammation of acute respiratory distress syndrome (ARDS), miR-381-3p presents a low expression, and KCNQ1OT1 silencing inhibition may attenuate LPS-caused ARDS inflammation via up-regulating miR-381-30 and modulating ETS2." (PMID 35246016, 2022). "However, another study proposed that KCNQ1OT1 functioned as an activator of inflammatory response by modulating neutrophil extracellular trap formation in LPS-induced acute respiratory distress syndrome." (PMID 34783627, 2021). "Furthermore, other research has also shown that lnc‐KCNQ1OT1 is able to negatively regulate IL‐6, TNF‐α, and IL‐10 expression in acute respiratory distress syndrome." (PMID 34761437, 2021).
atrial fibrillation (4 papers, 2020 to 2025). A disorder characterized by an electrocardiographic finding of a supraventricular arrhythmia characterized by the replacement of consistent P waves by rapid oscillations or fibrillatory waves that vary in size, shape and timing and are accompanied by an irregular ventricular response. "One study revealed that the overexpression of lncRNA KCNQ1OT1 mediated the upregulation of L-type Ca2+ channels, CACNA1C, by binding miR-384 in angiotensin-II induced atrial fibrillation." (PMID 37709486, 2023).
cardiac hypertrophy (4 papers, 2020 to 2023). "For instance, inhibition of KCNQ1OT1 by hsa-miR-140-3P exacerbates ischemia–reperfusion injury, and hsa-miR-140-3p inhibits cardiac hypertrophy through targeting Gata4." (PMID 37626628, 2023). "For example, KCNQ1OT1 depletion could suppress cardiac hypertrophy by sponging miR-2054 and decreasing AKT3 expression." (PMID 36100884, 2022).
cholangiocarcinoma (4 papers, 2020 to 2021). A carcinoma that arises from the intrahepatic biliary tree (intrahepatic cholangiocarcinoma) or from the junction, or adjacent to the junction, of the right and left hepatic ducts (hilar cholangiocarcinoma). "In previous studies, KCNQ1OT1 facilitated progression of cholangiocarcinoma (CCA) by sponging miR-140-5p and regulating SOX4 expression." (PMID 32377169, 2020).
diabetic nephropathy (4 papers, 2020 to 2023). "Recently, KCNQ1OT1 expression in diabetic nephropathy was increased and associated with activation of MEK/ERK pathway in diabetic nephropathy." (PMID 36313695, 2022). "Another group identified that lncRNA KCNQ1OT1 was abnormally elevated in PBMCs of diabetic nephropathy, which was correlated with the activation of MEK/ERK pathway." (PMID 36313695, 2022). "In addition, a prior study uncovered that KCNQ1OT1 was overexpressed in diabetic nephropathy and that its silencing depressed proliferation and fibrosis and elevated apoptosis in diabetic nephropathy cells." (PMID 36937538, 2023). "In addition, KCNQ1OT1 was reported to accelerate diabetic nephropathy development via modulating miR-93-5p/ROCK2 axis." (PMID 36313695, 2022). "One study showed that KCNQ1OT1 participated in governing fibrosis, apoptosis and proliferation via regulation of miR-18b-5p and SORBS2 and NF-κB in diabetic nephropathy." (PMID 36313695, 2022). "dissected that KCNQ1OT1 governed cell oxidative stress, proliferation, inflammation and extracellular matrix enhancement through miR-147a/SOX6 pathway in diabetic nephropathy." (PMID 36313695, 2022).
infertile (4 papers, 2016 to 2022). "The DNA methylation of one paternally (H19) and two maternally (SNRPN and KCNQ1OT1) methylated imprinted genes in sperm samples from 97 infertile males and 31 control subjects was analyzed by bisulfite pyrosequencing." (PMID 29136648, 2017). "Intriguingly, gain of methylation at mICRs (e.g., KCNQ1OT1, MEST, PLAGL1 and SNRPN) and loss of methylation at pICRs (e.g., H19) are frequently observed in spermatozoa from infertile human patients." (PMID 27880848, 2016).
Silver-Russell syndrome (4 papers, 2017 to 2024). Silver-Russell syndrome is characterized by growth retardation with antenatal onset, characteristic facies and limb asymmetry. "Their deregulated expression is the cause of Beckwith–Wiedemann syndrome (H19, IGF2, KCNQ1OT1), Russel-Silver syndrome (H19, IGF2, KCNQ1OT1) and Uniparental disomy 14 (MEG3) and is also observed in several tumors." (PMID 31143763, 2019).
Arrhythmia (3 papers, 2018 to 2021). Any cardiac rhythm other than the normal sinus rhythm. "The long non-coding RNA Kcnq1ot1 is involved in different pathophysiological mechanisms of multiple diseases, including acute myocardial damage and arrhythmia." (PMID 30250027, 2018).
asthma (3 papers, 2021 to 2023). "The detection of serum lncRNA KCNQ1OT1 can be used to monitor the occurrence and progression of airway remodeling in childhood asthma, thus providing a new idea and diagnostic tool for asthma therapy." (PMID 34635022, 2021). "In the network, the lncRNAs KCNQ1OT1 and NEAT1 compete with all miRNAs and have the potential to be key targets in the treatment of AR and asthma." (PMID 36733482, 2023). "We also identified fifteen DE long non-coding RNAs (lncRNAs) such as KCNQ1OT1, TMEM161B-AS1, GABPB1-AS1, AC137932.1, AC003681.1, MIR29B2CHG, Z95331.1, HOXB-AS2, AC103702.1, SAP30L-AS1, ZNF337-AS1, ARAP1-AS2, BX322234.1, LINC00886, and LOXL1-AS1 (padj < 0.1) relevant to asthma in our study." (PMID 34257337, 2021).
cataract (3 papers, 2018 to 2022). Partial or complete opacity of the crystalline lens of one or both eyes that decreases visual acuity and eventually results in blindness. "Research has suggested that the key function of KCNQ1OT1 in long QT syndrome, cataracts, cancers and Beckwith‐Wiedemann also some observations have suggested the KCNQ1OT1 as an oncogenic molecule in cancer." (PMID 35266286, 2022). "In addition, KCNQ1OT1 was significantly up-regulated in cataracts." (PMID 35170373, 2022).
colon adenocarcinoma (3 papers, 2021 to 2024). "LncRNA KCNQ1OT1 might affect tumor prognosis through CD8+ T cell infiltration in patients with colon adenocarcinoma." (PMID 36894542, 2023).
long QT syndrome (3 papers, 2018 to 2022). "The dysregulation of KCNQ1OT1 has been recognized in the pathology of electrophysiological disorders, including long QT syndrome, various arrhythmias, and the development of atherosclerotic plaques." (PMID 35246252, 2022). "Experimentally, siRNA-mediated knockdown of KCNQ1OT1 has been shown to lead to an increased action potential duration (APD) in vitro, while similar approaches used in vivo resulted in Long QT Syndrome (LQTS)." (PMID 35246252, 2022).
lymph node metastasis (3 papers, 2009 to 2021). "The analysis results showed that KCNQ1OT1 expression level was positively associated with advanced stage, lymph node metastasis, distant metastasis, or vascular invasion (p < 0.05)." (PMID 34350172, 2021). "Higher KCNQ1OT1 shortened overall survival and was positively associated with tumor stage and lymph node metastasis." (PMID 32377169, 2020).
neuroblastoma (3 papers, 2015 to 2022). Neuroblastoma (NB) is the most common solid, extracranial childhood tumor. "miR‐296‐5p can be sponged by KCNQ1OT1 and reverse its effect on neuroblastoma cell apoptosis." (PMID 35592755, 2022).
oral squamous cell carcinoma (3 papers, 2020 to 2021). "Further, KCNQ1OT1 facilitated invasion and inhibited apoptosis in oral squamous cell carcinoma by regulating the miR-185-5p/Rab14 axis." (PMID 34917682, 2021). "For instance, KCNQ1OT1 was found to regulate Rab14 expression, a target of miR-185-5p, in oral squamous cell carcinoma cells as a ceRNA." (PMID 33224264, 2020).
osteoporosis (3 papers, 2021 to 2023). A condition of reduced bone mass, with decreased cortical thickness and a decrease in the number and size of the trabeculae of cancellous bone (but normal chemical composition), resulting in increased fracture incidence. "This study was aimed at investigating the role of ADSCs-Exos and KCNQ1OT1 played in osteoporosis as well as the underlying mechanism." (PMID 34712334, 2021). "This study was aimed at investigating the role of ADSCs-Exos and a novel long noncoding RNA KCNQ1OT1 played in osteoporosis as well as the underlying mechanism." (PMID 34712334, 2021). "However, few studies have investigated the potential role of KCNQ1OT1 in the treatment of osteoporosis." (PMID 34712334, 2021). "KCNQ1OT1-Exos have a more significant inhibitory effect compared to ADSCs-Exos by the function of sponging miR-141-5p, suggesting that KCNQ1OT1-Exos can be promising agents in osteoporosis treatment." (PMID 34712334, 2021). "Thus, KCNQ1OT1-Exos are expected to be promising candidates in osteoporosis treatment." (PMID 34712334, 2021). "Therefore, we are curious whether KCNQ1OT1 can play a positive role in the treatment of osteoporosis." (PMID 34712334, 2021). "In summary, this study suggests that KCNQ1OT1, as a sponge for miR-128-3p, inhibits the osteoclast differentiation of RAW 264.7 cells through NFAT5 activation, which might provide a promising therapeutic approach to the prevention and treatment of osteoporosis." (PMID 35587369, 2022).
Adrenocortical tumors (2 papers, 2014 to 2020). "Adrenocortical tumors have a percentage of 3% in BWS cases, and few of them are associated with the LOM KCNQ1OT1 gene." (PMID 33101381, 2020). "Two cases of KCNQ1OT1 LOM with adrenocortical tumors also recently observed, and an additional one recently reported, although neither of these patients presented typical phenotypic features of BWS." (PMID 33101381, 2020).
cerebral infarction (2 papers, 2019 to 2024). An ischemic condition of the brain, producing a persistent focal neurological deficit in the area of distribution of the cerebral arteries. "For instance, lncRNA KCNQ1OT1 aggravates cerebral infarction by sponging miR-16-5p, leading to polypyrimidine tract binding protein 1 activation and subsequent SIRT1 downregulation in BMECs associated with inflammation and diminished angiogenesis." (PMID 39598406, 2024). "Cerebral infarction or ischemia has been shown to elevate lncRNA KCNQ1OT1, MALAT1, NEAT1, and Snhg12, while suppressing Snhg8." (PMID 39598406, 2024). "In vivo experiments revealed that KCNQ1OT1 knockdown hindered cerebral infarction and neurological deficits." (PMID 30945454, 2019).
Cerebral ischemia (2 papers, 2022). Restriction of arterial blood supply to the brain associated with insufficient oxygenation to support the metabolic requirements of the tissue. "In cerebral ischemia–reperfusion injury, silencing KCNQ1OT1 would attenuate endoplasmic reticulum stress via regulating the downstream miR-30b/GRP78 signaling cascade." (PMID 36278219, 2022).
cervical cancer (2 papers, 2021). A primary or metastatic malignant neoplasm involving the cervix. "Literature reports that lncRNA KCNQ1OT1 is markedly up-regulated in cervical cancer (CC) tissues and cell lines, and KCNQ1OT1 can promote the proliferation and metastasis of CC cells." (PMID 34704918, 2021). "KCNQ1OT1 is upregulated in cervical cancer (CC) patient cancerous tissues and cell lines, and its high expression is significantly correlated with increased tumor volume and poor differentiation in cervical cancer patients." (PMID 34827600, 2021).
colorectal adenocarcinoma (2 papers, 2021 to 2024). The most common type of colorectal carcinoma. "Differential gene expression analysis showed distinct gene expression patterns in GCA compared to colorectal adenocarcinoma, with a number of cancer-related differentially expressed genes, including upregulation of TMEM14A, GOLT1A, DSCC1, and HSD17B8, and downregulation of KCNQ1OT1 and MXRA5." (PMID 34804955, 2021).
diabetic retinopathy (2 papers, 2022 to 2023). "In addition, KCNQ1OT1 is an important prognostic marker in diabetic retinopathy, osteolysis, and other diseases." (PMID 37326687, 2023). "Reportedly, lncRNA KCNQ1-overlapping transcript 1 (KCNQ1OT1) was involved in the development of diabetic retinopathy (DR) by promoting proliferation and angiogenesis of hRECs through sponging miR-1470; and knockdown of KCNQ1OT1 induced apoptosis and inhibited cell proliferation in HG." (PMID 35517509, 2022).
head and neck squamous cell carcinoma (2 papers, 2021 to 2024). A squamous cell carcinoma that arises from any of the following anatomic sites: lip and oral cavity, nasal cavity, paranasal sinuses, pharynx, larynx, and salivary glands. "The prediction of TCGA link in the UALCAN database showed that lncRNA KCNQ1OT1 is highly expressed in head and neck squamous cell carcinoma." (PMID 39039611, 2024).
heart failure (2 papers, 2022 to 2024). Inability of the heart to pump blood at an adequate rate to meet tissue metabolic requirements. "The lncRNA KCNQ1OT1 directly targets the FUS protein and negatively regulates its protein level, thus facilitating cardiomyocyte apoptosis in heart failure." (PMID 35974003, 2022).
laryngeal squamous cell carcinoma (2 papers, 2022). A squamous cell carcinoma that arises from the larynx. "Our research investigated the role and mechanism of the m6A modification of lncRNA KCNQ1 overlapping transcript 1 (KCNQ1OT1) in Laryngeal squamous cell carcinoma (LSCC) progression." (PMID 34850551, 2022).
leukemia (2 papers, 2020 to 2021). A malignant (clonal) hematologic disorder, involving hematopoietic stem cells and characterized by the presence of primitive or atypical myeloid or lymphoid cells in the bone marrow and the blood. "Our results describe an important role of KCNQ1OT1 in mediating c-Myc-induced leukemia cell proliferation and enrich the mechanism of how c-Myc contributes to APL pathogenesis." (PMID 34404765, 2021). "Other loss of function studies showed that KCNQ1OT1 is required for cell proliferation and survival and that loss of KCNQ1OT1 promotes cell differentiation in AML cells, a feature which makes it attractive as a therapeutic target for this type of leukemia." (PMID 33134177, 2020).
long-QT syndrome type 1 (2 papers, 2013 to 2018). "On the paternal chromosome, inhibition of CDKN1C is associated with the expression of a long noncoding RNA called KCNQ1OT1 or LIT1 antisense to KCNQ1, the potassium channel gene involved in long-QT-syndrome type 1 and Jervell/Lange-Nielsen syndrome." (PMID 23572028, 2013).
nasopharyngeal carcinoma (2 papers, 2024). A carcinoma arising from the nasopharyngeal epithelium. "Moreover, KCNQ1OT1 is up-regulated in DDP-resistant nasopharyngeal carcinoma cells, with the potential to treat patients with DDP-resistant nasopharyngeal carcinoma." (PMID 39039611, 2024).
osteoarthritis (2 papers, 2020 to 2025). A noninflammatory degenerative joint disease occurring chiefly in older persons, characterized by degeneration of the articular cartilage, hypertrophy of bone at the margins and changes in the synovial membrane. "A recent literature showed that KCNQ1OT1 showed upregulation and downregulation effects on the inflammatory response in patients with osteoarthritis by interacting with miR-126-5p and miR-211-5p, respectively." (PMID 40606658, 2025).
Pituitary Adenoma (2 papers, 2021 to 2022). "This study is aimed at investigating the effect and mechanism of long noncoding RNA (lncRNA) KCNQ1OT1 on pituitary adenoma (PA)." (PMID 35432529, 2022). "Additionally, KCNQ1OT1 was reported to participate in the activation of p38/NF-κB pathway in pituitary adenomas and acute myocardial injury." (PMID 34783627, 2021).